LCE3C (late cornified envelope 3C)
Description:
A structural component of the cornified envelope of the stratum corneum involved in innate cutaneous host defense (Probable). Possesses defensin-like antimicrobial activity against a broad spectrum of Gram-positive and Gram-negative bacteria, both aerobic and anaerobic species. Upon inflammation, may regulate skin barrier repair by shaping cutaneous microbiota composition and immune response to bacterial antigens.
Synonyms: LEP15; SPRL3A
Tractability: No criterion of Open Targets' tractability assessment is met for any kind of drug.
Gene: Protein-coding gene on chromosome 1 (152,600,234 to 152,601,086, forward strand). Ensembl gene ENSG00000244057.
Pathways (Reactome):
Developmental Biology: Formation of the cornified envelope
Gene Ontology:
Molecular function: protein binding
Biological process: defense response to Gram-negative bacterium; defense response to Gram-positive bacterium; killing of cells of another organism; epidermis development
Homologues: Orthologues: chimpanzee LCE3C (96% identical), rabbit LCE3A (76% identical). Paralogues in human: LCE3D (83% identical), LCE3E (81% identical), LCE3B (80% identical), LCE3A (78% identical), LCE1E (62% identical), LCE5A (61% identical), LCE1F (59% identical), LCE2A (59% identical), LCE2C (59% identical), LCE2D (59% identical), LCE2B (57% identical), LCE1D (56% identical), and 8 more.
Diseases named in the same sentence as LCE3C in open-access papers:
LCE3C is named in the same sentence as 5 diseases in open-access papers, as found by Europe PMC text mining. Sharing a sentence is not in itself a finding about the gene and the disease. The quoted sentences say what the papers report.
psoriasis (12 papers, 2010 to 2023). An autoimmune condition characterized by red, well-delineated plaques with silvery scales that are usually on the extensor surfaces and scalp. "Many of the human genes overlapping with ZCRs in our study have known presence/absence variation among human populations, such as LCE3B and LCE3C, which are associated with antimicrobial activity and implicated in psoriasis and wound-healing." (PMID 37179373, 2023). "Other human genes such as LCE3B and LCE3C overlapped ZCRs in some samples, for example, a 30 kb nearly continuous region linked to psoriasis that was identified in the CHM1 haploid genome." (PMID 37179373, 2023). "Genetic studies indicate a role for skin barrier dysfunction in psoriasis since deletion of LCE3B and LCE3C genes, encoding stratum corneum proteins involved in terminal differentiation of the epidermis, was found to be associated with psoriasis." (PMID 26573299, 2016). "Genetic variations in ERAP1, IL23R, and LCE3B/LCE3C have recently been associated with pediatric-onset psoriasis (onset < age 18) in a small study." (PMID 24175098, 2013). "Our results not only point to a possible role for LCE3C in the genetic risk of psoriasis, but also suggest local skin inflammation could modify this pathway to contribute to psoriatic disease." (PMID 37805522, 2023). "A common, 32kb deletion of LCE3B and LCE3C genes is strongly associated with psoriasis." (PMID 27919236, 2016). "LCE genes, specifically LCE3B and LCE3C, located in the PSORS4 locus, have been shown to be related with psoriasis risk by both copy number variation studies and GWAS." (PMID 37628670, 2023). "It was demonstrated that deletion in late cornified envelope genes, LCE3B and LCE3C, located within PSORS4 is a genetic risk factor of psoriasis, suggesting disruption of the differentiation process in psoriasis." (PMID 35054853, 2022). "An association between a common deletion comprising the late cornified envelope LCE3B and LCE3C genes (LCE3C_LCE3B-del) and Psoriasis (Ps) has been reported." (PMID 20331852, 2010). "It is unknown how the lack of LCE3B and LCE3C activity due to their deletion leads to psoriasis susceptibility." (PMID 27919236, 2016). "In lesional psoriasis skin, the expression of LCE3A, LCE3B and LCE3C is markedly increased, which is consistent with our findings." (PMID 34440590, 2021). "In psoriasis patients, the majority of whom harbor genomic deletion of LCE3B and LCE3C (LCE3C_LCE3B-del), we propose that certain dietary analogues of 1,25D activate the expression of residual LCE3A/LCE3D/LCE3E genes to compensate for the loss of LCE3B/LCE3C in the deletant genotype." (PMID 29401702, 2018).
diabetes (1 paper, 2020). "The effects of diabetes were partly mediated by the altered methylation of HOOK2, LCE3C, and TMEM63B." (PMID 32075680, 2020).
lung adenocarcinoma (1 paper, 2020). A carcinoma that arises from the lung and is characterized by the presence of malignant glandular epithelial cells. "In this study, for the first time, LCE3C was found to be a new prognostic marker for lung adenocarcinoma." (PMID 32596344, 2020).
tumor (1 paper, 2020). "However, LCE3C has not been shown to be associated with tumor." (PMID 32596344, 2020).
LCE3C also shares sentences with these, for which no sentence is quoted: periodontitis (1 paper).